ENSG00000251730
Gene: Small nucleolar RNA gene on chromosome 3 (183,454,128 to 183,454,262, forward strand). Ensembl gene ENSG00000251730.
Homologues: Paralogues in human: SNORA4 (65% identical).